TNF (tumor necrosis factor)
Diseases named in the same sentence as TNF in open-access papers (continued):
Sharing a sentence is not in itself a finding about the gene and the disease.
myocardial infarction (continued). "The early inflammatory phase following myocardial infarction with soaring levels of TNF-α may provide basis for the delayed increase of CCN5 relative to CCN2." (PMID 34854055, 2022). "Moreover, pretreatment with atorvastatin significantly reduces plasma IL-6 and TNF-α levels as well as Rho-kinase activity, myocardial infarct size, and cardiomyocyte apoptosis." (PMID 36684592, 2022). "However, another study reported that TNF-α played a protective role in the early-stage of myocardial infarction in line with the regulation of autophagy and apoptosis." (PMID 35693778, 2022). "Moreover, decreases in the levels of TNF-α and IL-1β, and increases in IL-10, were also shown in a rat model of myocardial infarction." (PMID 35161351, 2022). "The mtDNA induced by myocardial infarction could inhibit the secretion of IL-6 and TNF-α in granulocytes, which may account for the patients’ susceptibility to infection after injury or myocardial infarction." (PMID 35454769, 2022). "For example, a 1-SD higher baseline serum level for each of IL-6, IL-18, and TNF-α is associated with a 10–25% higher risk of non-fatal myocardial infarction (MI) or coronary heart disease (CHD) death." (PMID 35997393, 2022). "Myocardial TNF-α was correlated with MMP-9 activity in a mouse model of myocardial infarction." (PMID 35372112, 2022). "Interestingly, a decline of inflammatory cytokines such as TNF-α in sera of patients treated with taVNS for depression, atrial fibrillation, and myocardial infarction has also been observed." (PMID 34599686, 2022). "TNF-α was considered to have proinflammatory effects via binding to its TNFR-1 and TNFR-2 receptors, and the expressions of TNFR1 and TNFR-2 were associated with higher risk of myocardial infarctions." (PMID 35425840, 2022). "A 2 week supplementation with red wine grape pomace reduced premature death, changed TNF-α and IL-10 levels, increased plasma antioxidant activity, and attenuated myocardial infarction and dysfunction, confirming the cardioprotective effect of red grape products in ischemic heart disease." (PMID 34072098, 2021). "Circulating CD14+HLA-DRneg/low monocytes secrete high levels of TNFα, IL-6, and IL-1β which promote proinflammatory immune responses; in the expansion of this monocyte population after myocardial infarction correlates with both cardiac damage and physiological function." (PMID 34589791, 2021). "TNF-α tissue levels are increased in the heart after myocardial infarction (MI)." (PMID 33770265, 2021). "Taken together, our results show that the odds of having a history of heart attack in presence of elevated triglycerides and pro-inflammatory parameters (TNFα and IL6) are approximately eight fold higher as compared to heart attack with elevation only in the levels of TNFα and IL6." (PMID 33510184, 2021). "Similarly, TNFα, MCP-1, and CCL-5 mediate pro-inflammatory effects via mechanisms associated with increased vascular injury leading to AD and myocardial infarction." (PMID 33626069, 2021). "In addition, a clinical study found that after revascularization of myocardial infarction, inflammatory factors in patients' serum including TNF-α, IL-1β, IL-6, and IL-8 were significantly increased." (PMID 34858542, 2021). "We further report that the odds of having heart attack in presence of elevated triglycerides and pro-inflammatory parameters (TNFα and IL6) were approximately eight times higher as compared to heart attack in individuals with only elevated levels of pro-inflammatory markers." (PMID 33510184, 2021). "TNF-α influences the production of other pro-inflammatory cytokines, such as IL-1 β and IL-6, resulting in a negative cycle of pro-inflammatory cytokine production and aggravation of injury after myocardial infarction." (PMID 33503060, 2021).
myocardial infarction (continued). "Elevations in TNF-α increase adipokines and vascular endothelial impairment, and decreases in glucose tolerance result in the progression of arteriosclerosis, thereby inducing myocardial infarction." (PMID 34441936, 2021). "MPC may also provide cardioprotection via the reduction in pro-inflammatory responses by reducing accumulation of neutrophils in the myocardial infarction zone, and/or decreasing plasma tumor necrosis factor alpha (TNFα) levels." (PMID 32024002, 2020). "However, this is at odds with a report of increased TACE expression and TNFα in localized samples of ruptured plaques in human acute myocardial infarction, which also indicates a more complex process beyond TNFα shedding alone." (PMID 32911849, 2020). "iRhom2 was shown to regulate TNF signaling and pro-inflammatory pathways in classically activated M1-like macrophages, which promote tissue regeneration and collagenous scar formation following myocardial infarction." (PMID 33330676, 2020). "In vivo experiments showed that GXV increases the ejection fraction and fractional shortening and reduces the left ventricular mass index and reduces the levels of IL-6, TNF-α and other inflammatory factors in rats with acute myocardial infarction by inhibiting the NF-κB pathway." (PMID 33187508, 2020). "In the current study, myocardial and serum levels of TNF- α in rats fed with high-fat diets and isoproterenol-induced myocardial infarction animals were evaluated to clarify the correlation between TLR4/MyD88 protein expressions in myocardium and production of proinflammatory cytokines." (PMID 32211137, 2020). "While these findings and studies showing that TNF-α knockout mice have decreased inflammation and improvements in cardiac remodeling and function following myocardial infarction suggest TNF-α neutralization would be beneficial in the injured heart, this has not been the case." (PMID 33041853, 2020). "For example, elevated CRP, TNF-α, and IL-6 levels have been associated with both myocardial infarction (MI) and non-traumatic FF." (PMID 30630495, 2019). "Finally, treatment with β-caryophyllene reduces the levels of the inflammatory markers TNF-α, IL-1β, and NFκB in heart tissue, which are elevated in isoproterenol-induced myocardial infarction." (PMID 31109132, 2019). "The increase in IL-10 in myocardial infarct patients was found to be correlated with systemic pro-inflammatory activity evaluated with thrombosis, plaque rupture and heart destruction related to IL-6 and TNF-α plasma concentrations." (PMID 29742255, 2018). "Using iRhom2-deficient mice, which lack myeloid-specific shedding of TNF-α, we reveal increased macrophages (MΦs) that were skewed towards a more proinflammatory (M1) state at day 4, followed by more reparative, antiinflammatory (M2) state at day 7 after myocardial infarction (MI)." (PMID 29415889, 2018). "Moreover, PLD1 plays a pivotal role in Tumor Necrosis Factor-alpha (TNF-α) mediated inflammation and scar formation after acute myocardial infarction in mice." (PMID 29968773, 2018). "Inflammatory biomarkers (tumor necrosis factor alpha and interleukin-6) were reduced and pro-angiogenesis factors (vascular endothelial growth factor and platelet/endothelial cell adhesion molecule 1) were augmented in the myocardial infarct and border area." (PMID 29751831, 2018). "Meta-analysis of cohort studies demonstrated that use of TNFα-i in RA patients is associated with a 30% relative reduction in all CV events and a 41% reduction of myocardial infarction in comparison to other non-biologic therapies." (PMID 30619884, 2018). "Furthermore, in a mouse model of myocardial infarction, TNF-α mRNA, IL-1α, IL-2, IL-4, IL-5, IL-6, IL-10, IL-17A, TNF-α, IFN-γ, and GM-CSF expression were all lower in the infarct area of TLR4-deficient mice compared with wild-type mice." (PMID 30399158, 2018).
myocardial infarction (continued). "These might partially explain the mechanism of why HMP decreases IL-6 and TNF-α in rats with acute myocardial infarction." (PMID 28373886, 2017). "In the current study myocardial TNF-α was measured 20 min after reperfusion only, supporting the previously made observation in a myocardial infarction heart model of two phases of reperfusion injury, an early one within the first 3 min and a later phase after 40–60 min." (PMID 28376800, 2017). "The current study investigated the effect of HMP on the concentrations of interleukin-6 (IL-6) and tumor necrosis factor-alpha (TNF-α) and observed the relationship between level changes of inflammatory cytokines and ventricular remodeling in rats with acute myocardial infarction (AMI)." (PMID 28373886, 2017). "Here, we demonstrated the over-expression of TNF-α, Fas and caspase-8 during myocardial infarction, suggesting that the three aforesaid expressions might play a role in myocardial apoptosis." (PMID 27021411, 2016). "Companying with same dose of SalB or Rg1 only, SalB-Rg1 showed more significant effects on down-regulation of myocardial infarct size, maintenance of myocardium structure, improvement on cardiac function, decrease of cytokine secretion including TNF-α, IL-1β, RANTES and sVCAM-1." (PMID 26280455, 2015). "The TNF-α bioactivity in the heart increases from the early stage of I/R; such increase has been speculated to partially contribute to the increased area of myocardial infarction." (PMID 26265983, 2015). "Human and mouse TSG-6 proteins share 92% sequence identity, and human recombinant TSG-6 has been shown to inhibit TNF expression in mouse macrophages in a co-culture experiment, and reduce inflammatory response and infarct size in a mouse model of myocardial infarction." (PMID 24423010, 2014). "In addition, patients with acute myocardial infarction showed higher TNF-α/IL-10 ratios when compared to the control group, demonstrating an important inflammatory imbalance." (PMID 25340545, 2014). "Several studies have illustrated that TNF-α could promote normal MSCs migration at the time of tissue damage such as myocardial infarction, tissue ischemia, and wound healing." (PMID 25762184, 2014). "Also, it was reported that QSYQ can inhibit inflammatory effect through reducing TNF-α and IL-6 levels in rat after acute myocardial infarction." (PMID 24817581, 2014). "In one study, TNF overexpression in mice promotes the development of post myocardial infarction left ventricular remodelling and contractile dysfunction, whereas other studies demonstrates the protective role of TNF signaling on myocardial cell apoptosis and on reducing infarct size." (PMID 23405158, 2013). "In this regard, results from the British Society for Rheumatology Biologics Register showed that the risk of myocardial infarction was markedly reduced in RA patients who responded to anti-TNF-alpha therapy by 6 months compared with nonresponders." (PMID 22899879, 2012). "In addition, fibrin beta decreases myocardial infarct size, scar formation, inflammation and the levels of cytokines (interleukin 1 beta, tumor necrosis factor-alpha and interleukin 6) in plasma." (PMID 23139772, 2012). "The expression of TNF-α increased greatly after acute myocardial infarction." (PMID 21584281, 2011). "Mechanical stress is associated with myocardial infarction triggering myocardial production of TNF and IL-6, not only in the infracted, but also in the non-infarcted region of the heart." (PMID 17592640, 2007). "This study was undertaken to test the hypothesis that the powerful antiinflammatory effect of anti–tumor necrosis α (anti-TNFα) therapy might lead to a reduction in the incidence of myocardial infarction (MI) in patients with RA." (PMID 17763428, 2007). "Moreover, nalbuphine could efficiently improve the hemodynamic perturbation in myocardial infarction and exert an anti-inflammatory potential via inhibiting NF-κB-induced IL-6 and TNF-α production." (PMID 39272237, 2024).
myocardial infarction (continued). "Furthermore, our data indicated that Turicibacter was obviously and negatively correlated with serum cTnI and CK levels, the myocardial infarct area, HE score, apoptosis rate, inflammatory factors (IL-1β, IL-6, and TNF-α) in colon and ileum and serum LPS and Zonulin concentration." (PMID 37656700, 2023). "The group receiving this treatment had improved cardiac contractility at 5 weeks post myocardial infarction and enhanced blood vessel density in the border zone of the infarct, decreased interstitial fibrosis, and reduced levels of the plasma pro-inflammatory cytokines (IL-6 and TNF-α)." (PMID 36263604, 2023). "Tumor necrosis factor (TNF) is known as tumor necrosis factor-alpha (TNF-α) which is a small cytokine protein that is involved in the development of coronary heart disease through inflammatory response, plaques, and coronary heart disease acute myocardial infarction." (PMID 36035865, 2022). "The study group also proceeded to a meta-analysis of the available evidence (29 studies), demonstrating an increased risk for non-fatal myocardial infarction or cardiovascular mortality per 1 standard deviation increased TNF-α levels (adjusted hazard ratio: 1.17, 95% confidence intervals 1.09–1.25)." (PMID 36555579, 2022). "Furthermore, TNF-α is also involved in adverse remodeling after myocardial infarction." (PMID 36060429, 2022). "Table. demonstrates the animal studies of RIC and cytokine release, performed within the last 5 years, following myocardial infarction and reperfusion Across several studies, RIC was associated with reduced levels of the pro-inflammatory cytokines, IL-1β, TNF-α and HMGB1 following reperfusion." (PMID 33629195, 2021). "Importantly, pro-inflammatory cytokine levels are elevated in the myocardium following myocardial infarction (including TNF-α, IL-1β, and IL-6), producing electrophysiological changes, suggesting that the persistent existence of inflammation is an important contributor to arrhythmia." (PMID 32116751, 2020). "TNF-α can affect the development of coronary heart disease through the following ways: participation in the inflammatory response of atherosclerotic plaques, the formation and rupture of plaques, leading to coronary heart disease and even acute myocardial infarction." (PMID 32046680, 2020). "Moreover, a meta-analysis of up to 29 population-based prospective studies, IL-6, IL-18, and TNF-α were all found to result in significantly higher relative risks for non-fatal myocardial infarction or CHD death after adjusting for traditional risk factors." (PMID 29750272, 2018). "Genetic variants in the TNF-α promoter region are reported to be associated with the TNF-α serum levels, these levels are correlated with the first-time cardiovascular disease and are also a marker for recurrent coronary events after a previous myocardial infarction." (PMID 26751459, 2016). "Also, the upregulation of pro-inflammatory cytokines, such tumor necrosis factor (TNF)α7 and interleukin (IL)-88, might initiate processes triggering increased cell trafficking, since myocardial infarction is associated with the inflammatory response." (PMID 28299177, 2016). "Further to the reduction of pro-inflammatory cytokines expression, statins up-regulate the expression of anti-inflammatory cytokine IL-10 and improve the balance between TNF-α / IL-10 post-myocardial infarction (MI) in rats." (PMID 22364136, 2012). "In the CARE trial in patients with a recent myocardial infarction (MI), those who experienced a recurrent MI or cardiac death had higher TNF-α levels than matched controls." (PMID 19690647, 2007). "In the mouse model of acute myocardial infarction, Ferulic acid can also inhibit the apoptosis of H9C2 cells induced by TNF-α or actinomycosterone via blocking ROS production and Caspase-3 activity." (PMID 39936089, 2025).
myocardial infarction (continued). "In cardiovascular diseases (such as myocardial infarction) and acute kidney injury (AKI), TNF-α exacerbates organ damage by promoting cardiomyocyte apoptosis and renal tubular epithelial cell necroptosis." (PMID 40661082, 2025). "For example, one study found a marked increase in TNF-α levels in ACS patients, with higher levels particularly in those with acute myocardial infarction (MI) compared to unstable angina, and these elevated levels correlated with greater complications." (PMID 41511355, 2025). "Post-myocardial infarction, exosomal miR-146a from transfected ADSCs directly suppressed early growth response factor 1 (EGR1) activation and IL-1β/-6 and TNF-α expression due to inhibition of the toll-like receptor 4 (TLR4)/NF-κB pathway." (PMID 40676634, 2025). "Reduced transcription of CCL2, expression of CD163+ macrophages, and modulation of immune response factors, including IL-1, PBMC influx, TNF-α, GM-CSF levels, and CD73+ and CCR2+ monocytes, further support EV’s therapeutic potential for myocardial infarction." (PMID 38790361, 2024). "In contrast, exosomes from adipose-derived MSCs exhibit reduced levels of inflammatory markers as IL-1β, IL-6, TNF-α, and IFN-γ in patients with myocardial infarction." (PMID 39911664, 2024). "In all cases of myocardial infarction, median serum levels of hs-CRP, IL-6, NF-κB, TNF-α and VCAM-1 were 1.31 mg/L, 11.88 pg/ml, 11.34 ng/ml, 2.19 pg/ml and 1157.37 ng/ml, respectively." (PMID 39351476, 2024). "Its primary action targets IL-10, with the protein–protein interactions analysis indicating interactions between IL-10 and key inflammatory mediators—IL-1β, IFN-γ, CCL2, TNF, and TGF-β1—during acute myocardial infarction and cardiac fibrosis." (PMID 39200761, 2024). "For example, miR-21 inhibits TNF-α-induced apoptosis via activating JNK/p38/caspase-3 signaling pathway, thereby promoting the occurrence of acute myocardial infarction in the elderly." (PMID 38699693, 2024). "The interaction between TNF-α and TNFR1 primarily contributes to the inflammatory response and ventricular remodeling in acute myocardial infarction (AMI), leading to cardiomyocyte apoptosis and cardiotoxicity." (PMID 39024234, 2024). "The expression of TNFα and iNOS was increased while the expression of VEGFA was reduced in the myocardial infarction group." (PMID 35548775, 2022). "A previous study showed that RIG-I activator TNF-α upregulated the expression of RIP3, which was sufficient to induce necroptosis of cardiomyocytes during myocardial infarction." (PMID 35693778, 2022). "In the myocardial infarction model, HSP20-regulated exosomes increase cell survival by activating Akt and decreasing mRNA levels of inflammatory factors such as TNF-α and IL-1β." (PMID 36036015, 2022). "This research sought to investigate the clinical significance of level changes of TLR2, TLR3, TLR4, TNF-α, sTNFR-1, sTNFR-2, EPCs, and VEGF in elderly patients with recurrent myocardial infarction after coronary stent implantation." (PMID 35425840, 2022). "In the heart, activation of the CaMKIIδC- KB kinase inhibitor (IKK)-NF-κB axis leads to increased expression of TNF-α, and inhibition of IKK or TNF-α is sufficient to reduce the size of myocardial infarction." (PMID 36036015, 2022). "We validated these findings by training a neural network of four factors TNFα, IL6, and triglycerides to predict heart attack." (PMID 33510184, 2021). "In order to validate these findings, we further used TNFα, IL6, and triglycerides to train a neural network for predicting heart attack." (PMID 33510184, 2021). "In acute myocardial infarction rat model, the combination of pFUS + MB results in increased expression of IL‐1β, 4, 6, MCP‐1 and TNF‐α within 15 minutes post‐sonication." (PMID 33067927, 2020). "Proatherogenic inflammatory cytokine tumor necrosis factor-α (TNF-α) was elevated in patients with unstable atherosclerotic lesions and acute myocardial infarction." (PMID 33029103, 2020).